FGF23 (fibroblast growth factor 23)
Diseases named in the same sentence as FGF23 in open-access papers (continued):
Sharing a sentence is not in itself a finding about the gene and the disease.
ovarian carcinoma (7 papers, 2011 to 2025). A malignant neoplasm originating from the surface ovarian epithelium. "In the two reported cases, epithelial ovarian cancer and teratoma were associated with hypophosphatemic osteomalacia and increase in FGF23." (PMID 38806758, 2024). "The literature review thus does not seem to provide conclusive evidence on the association between ovarian cancer, FGF23, and the development of TIO." (PMID 38806758, 2024). "Case-control studies evaluated the association of FGF23 concentrations with ovarian cancer stage and of various FGF single nucleotide polymorphisms (SNPs) with cancer development risk, survival, and therapeutic response." (PMID 38806758, 2024). "We reported a case of high-grade ovarian carcinoma associated with an elevated serum FGF23 level and hyperphosphaturic hypophosphatemic osteomalacia, which has not been previously reported in the literature to our knowledge." (PMID 25181387, 2014). "In conclusion, a subset of ovarian cancer cases may be associated with elevated FGF23 levels and should be taken into account during the differential diagnosis of TIO." (PMID 25181387, 2014). "In our study, several CRGs identified in ovarian cancer, including FGF23 56 and AGFG1 57, are involved in drug metabolism." (PMID 40861807, 2025). "Approximately half of the patients with advanced-stage ovarian cancer had elevated serum FGF23 levels before treatment." (PMID 25181387, 2014). "After surgery and chemotherapy treatments for ovarian cancer, the serum phosphate and FGF23 levels returned to normal, and the low back pain improved." (PMID 25181387, 2014). "Clinicians should have vigilance to measure serum phosphorus and/or FGF23 in patients with ovarian cancer, especially those with advanced-stage cancer or those with weakness, bone pain, and fracture." (PMID 25181387, 2014). "The patient's serum phosphate and FGF23 levels were evaluated at baseline and after treatment for ovarian cancer." (PMID 25181387, 2014). "In addition, elevated serum or plasma FGF23 levels have been documented in women with advanced-stage ovarian cancer when compared to concentrations in women with early-stage ovarian cancer, benign disease, or in healthy women." (PMID 38806758, 2024). "Immunohistochemistry also detected FGF23 tissue staining in malignant ovarian cancer cells." (PMID 38806758, 2024). "Moreover, FGF23 was detected in tissue staining in malignant ovarian cancer cells." (PMID 38806758, 2024). "In a study of 13 women with advanced-stage ovarian cancer, 14 with early-stage ovarian cancer, 14 with benign ovarian tumors, and 39 healthy women, serum FGF23 levels were higher in patients with advanced-stage ovarian cancer, without decreased serum phosphate levels." (PMID 25181387, 2014).
rheumatoid arthritis (7 papers, 2018 to 2024). A chronic, systemic autoimmune disorder characterized by inflammation in the synovial membranes and articular surfaces. "In rheumatoid arthritis, FGF23 enhanced a proinflammatory cytokine, IL-1β, in synovial fibroblasts through FGF23-FGFR1c-mediated PI3K-Akt and NF-κB pathways promoting joint pain, swelling, and bone deformities." (PMID 39766329, 2024). "According to our study, myostatin inhibition could result in lower FGF23, which may indeed be beneficial with regard to the reduced bone mass typical of both Duchenne muscular atrophy and rheumatoid arthritis." (PMID 33895875, 2021). "A correlation between elevated levels of serum FGF23 in rheumatoid arthritis (RA) patients with disease activity and bone resorption has been established because serum RA enhances osteocyte-mediated osteoclastogenesis." (PMID 32708317, 2020). "In their investigation Sato and co-authors could not detect a correlation of FGF23 with glucocorticoid doses in rheumatoid arthritis." (PMID 33546660, 2021).
thalassemia (7 papers, 2018 to 2025). An inherited blood disorder characterized by a decreased synthesis of one of the polypeptide chains that form hemoglobin. "Establishing a TDT-specific reference range for FGF23 would aid in interpreting biochemical data and improving the understanding of the FGF23 role in thalassemia-associated endocrine complications, particularly thalassemic bone disease." (PMID 40142640, 2025). "The present finding was consistent with the previous reports of the elevated level of FGF-23 in thalassemia being associated with iron utilization." (PMID 35396390, 2022). "Although the reduction in calcium absorption is often explained by thalassemia-associated hypoparathyroidism, low vitamin D production and interference from iron hyperabsorption, it could also be due to an increase in fibroblast growth factor (FGF)-23." (PMID 35396390, 2022). "Moreover, a rise in FGF23 in patients with thalassemia, might be either associated with the stimulating effect of PTH and 1,25(OH)2D3, or directly related to the stimulating effect of ferritin." (PMID 33198660, 2020). "The influence of Fe overload in thalassemia on P metabolism and FGF23 concentration was assessed in the current study." (PMID 39982925, 2025). "This study evaluates the effects of ferritin on intact PTH, FGF23, and l,25(OH)2D3 in patients with major thalassemia." (PMID 33198660, 2020). "Another finding of the present study was the high level of serum FGF23 in patients with thalassemia." (PMID 33198660, 2020). "Elevated levels of the FGF23 have been related to lower bone mineral density (BMD) and greater risk of fractures in Patients with thalassemia major." (PMID 33198660, 2020). "Thalassemia markedly increased serum FGF23 levels as observed in sham BKO mice compared to sham WT controls." (PMID 32385316, 2020). "The present study suggested that the rise in FGF23 in patients with thalassemia may be associated with either the stimulating effect of PTH and 1,25(OH)2D3 on FGF23 production, or direct induction effect of ferritin." (PMID 33198660, 2020). "In addition, impaired FGF-23 production, secondary to iron deposits in bones, might partly contribute to elevated serum P in thalassemia." (PMID 29726397, 2018). "In-depth studies should explore the complex link between iron overload, FGF-23, and the Ca-P-PTH axis in thalassemia, investigating mechanisms, mineral metabolism, and clinical results." (PMID 39982925, 2025). "However, there is a lack of sufficient data evaluating the association or interaction between high serum ferritin and levels of serum l,25(OH)2D3, FGF23 and PTH in patients with thalassemia." (PMID 33198660, 2020). "However, to our knowledge, the impact of an iron overload state on FGF-23 level, secondary to thalassemia or hereditary hemochromatosis, has not been reported." (PMID 29726397, 2018). "A correlation study in BKO mice further revealed that the serum FGF-23 levels were inversely correlated with the cardiac iron content, thus agreeing with our hypothesis that the increased FGF-23 level might be a compensatory response to iron overload in thalassemia." (PMID 35396390, 2022). "However, the mode of FGF-23- P axis control in thalassemia has not been elucidated." (PMID 29726397, 2018).
autosomal dominant polycystic kidney disease (6 papers, 2014 to 2026). Autosomal dominant form of polycystic kidney disease. "Of note, it is known that resistance to the elevated FGF23 may occur in some diseased conditions, such as autosomal dominant polycystic kidney disease." (PMID 25200959, 2014). "Even in patients with autosomal dominant polycystic kidney disease (ADPKD), lower levels of alkaline phosphatase and PTH together with higher circulating intact FGF-23 (iFGF-23) and decreased bone formation rate have been demonstrated." (PMID 39684548, 2024). "Furthermore, a clinical study with patients suffering from autosomal dominant polycystic kidney disease (ADPKD)—the most common cause of genetic CKD—showed a significantly elevated expression of hepatic FGF23, accompanied by increased circulating FGF23." (PMID 33989306, 2021). "FGF23 is also produced by non-osseous tissues, including pathological conditions of kidney and liver, e.g. FA-AKI, CCl4-ALI, autosomal dominant polycystic kidney disease and childhood biliary atresia [24,25,]." (PMID 38479224, 2024).
calcinosis (6 papers, 2020 to 2025). Deposition of calcium in the tissues. "In addition, higher serum fibroblast growth factor-23 (FGF-23) levels have also been found in SSc female patients with calcinosis." (PMID 37243003, 2023). "Calcinosis is not a typical manifestation of FGFR inhibitor-associated toxicity as the action of FGF23 is not completely blocked by FGFR inhibitors." (PMID 34199304, 2021). "Similarly, patient 7, who had normal pulp morphology, did not have a GALNT3 or FGF23 mutation, and did not have findings consistent with a KLOTHO mutation, had classic calcinosis findings, a markedly elevated cFGF23, and a blood phosphate that was at the upper limit of the normal range." (PMID 33977199, 2021).
cystic fibrosis (6 papers, 2016 to 2023). Autosomal recessive disorder caused by pathogenic variants in the CFTR gene (cystic fibrosis transmembrane conductance regulator), which encodes a chloride and bicarbonate channel expressed in epithelial cells, and follow the diagnosis criteria. "Previous authors have shown that FGF23 acts upon cystic fibrosis human bronchial epithelial cells and leads to the secretion of IL-8, which is an important cytokine driving chronic inflammation in these patients." (PMID 37637614, 2023). "Since patients with cystic fibrosis have elevated serum FGF23 levels, it is possible that by targeting the lung and other tissues, such as the liver, FGF23 contributes to the systemic inflammation that is common in this disease." (PMID 29770125, 2018). "Interestingly, the FGF23 effect only occurs in bronchial epithelial cells isolated from patients with cystic fibrosis, suggesting that the priming of cells by disease-specific stimuli might be necessary for FGF23 responsiveness." (PMID 29770125, 2018).
hearing loss (6 papers, 2014 to 2025). "No studies have looked at burosumab, a monoclonal antibody that inhibits FGF23, and its effect on the development of hearing loss in individuals with XLH." (PMID 41445554, 2025). "Our previous study demonstrated that high levels of FGF23 are associated with hearing impairment in ESRD patients, independently of Klotho." (PMID 36649363, 2023). "In addition, the risk of hearing impairment is significantly higher in ESRD patients with higher FGF23 levels than in those with lower FGF23 levels, which is consistent with the results of this study." (PMID 36649363, 2023). "Also, elevated FGF23 and D-serine were identified as risk factors for hearing impairment in ESRD, with ORs of 16.54 (95%CI, 2.75–99.55) and 15.22 (95%CI, 2.59–89.51), respectively." (PMID 36649363, 2023). "Potential contributions of PHEX and FGF23 to hearing loss were confounded because both mutations extended beyond the Phex coding region, and Gy mutations affected the nearby SmS gene, which has been associated with hearing loss." (PMID 30808384, 2019). "The impact of treatment, either with conventional therapy or FGF-23 inhibition, on hearing impairment is also unclear." (PMID 41445554, 2025). "MHD patients showed abnormally high expression of FGF23 and D-serine, where FGF23 and D-serine levels were significantly higher in the group with hearing impairment than in the group with normal hearing and normal controls (all P<0.01)." (PMID 36649363, 2023). "In the present study, we found that FGF23/D-serine levels were significantly higher in MHD patients with hearing impairment than in those with normal hearing and healthy subjects." (PMID 36649363, 2023). "The risk of hearing impairment in MHD patients with abnormally high expression of FGF23 and D-serine was 16.54 and 15.22 times higher than in MHD patients with lower FGF23 and D-serine levels, respectively." (PMID 36649363, 2023). "The hearing impairment in ESRD patients was associated with the degree of kidney injury, and serum FGF23 level." (PMID 34721981, 2021). "As such, more work is needed to fully elucidate the molecular links between FGF23, XLH and hearing loss." (PMID 30808384, 2019). "The serum levels of FGF23, phosphorus, and parathyroid hormone (PTH) in ESRD patients with hearing impairment significantly increased compared with those with normal hearing and healthy controls." (PMID 34721981, 2021). "This study aimed to investigate the relationship between the FGF23 and ESRD accompanied with hearing impairment." (PMID 34721981, 2021). "Furthermore, among the three study groups, the highest levels of FGF23 and D-serine were found in the MHD group with hearing impairment, followed by the group with normal hearing in MHD (all P < 0.01)." (PMID 36649363, 2023). "However, the correlation between FGF23 level and CKD patients with hearing impairment remains elusive." (PMID 34721981, 2021).
hepatocellular carcinoma (6 papers, 2017 to 2024). A malignant tumor that arises from hepatocytes. "Increased human FGF23 levels have been shown to predict mortality in patients waiting for liver transplant, and are associated with progression of hepatocellular carcinoma." (PMID 35231062, 2022). "Those constructs were transfected in human hepatoma cells (Huh-7) in parallel with native human FGF23 and wild-type (WT) and codon-optimized versions of cFGF23 coding DNA fused with the FGF23 native signal peptide or sp7." (PMID 34705504, 2021). "In human HepG2 hepatoma cells, we observed that FGF23 was expressed under hypoxia, implying that hypoxia can induce the expression of FGF23 in the liver in mammals." (PMID 28074842, 2017). "Progression of hepatocellular carcinoma (HCC) is not linked to altered FGF23 expression." (PMID 33520985, 2020). "Next, we treated immortalized mouse hepatocytes (AML12) and human hepatoma cells (Huh7) with CB1R agonist ACEA and tested ERRγ and FGF23 gene expression in a time-dependent manner." (PMID 38479224, 2024).
Hypomagnesemia (6 papers, 2015 to 2023). An abnormally decreased magnesium concentration in the blood. "In cats with azotemic CKD, hypomagnesemia was associated with a higher plasma FGF-23 concentration and an increased risk of mortality." (PMID 37893926, 2023). "First, mice with diet-induced hypomagnesemia have increased serum FGF23 levels and reduced renal Klotho expression, suggesting that dietary Mg2+ can influence the regulation of the FGF23-Klotho axis." (PMID 36699036, 2022). "Hypomagnesemia and high FGF-23 levels are independent predictors of mitral valve calcification and IMT and are risk factors for cardiovascular mortality in this population." (PMID 26089881, 2015). "Nevertheless, serum phosphate levels start to normalize within the first few months after KT due to the reduced FGF-23 levels, while hypomagnesemia might persist for several years after KT." (PMID 33919913, 2021).
iron overload (6 papers, 2018 to 2025). "Insights into the potential resistance to FGF23’s activities caused by iron overload may be especially valuable in treating complex disorders such as familial hypophosphatemia, which we want to establish through further longitudinal investigations." (PMID 39982925, 2025). "While the literature provides evidence on the link between FGF23, iron homeostasis and erythropoiesis, little is known about the FGF23 level variations in patients with ineffective erythropoiesis and iron overload, such as those with βT." (PMID 40142640, 2025). "Little is known about the FGF23 level variations in β-thalassemia (βT), which is characterized by ineffective erythropoiesis and iron overload." (PMID 40142640, 2025).
kidney injury (6 papers, 2015 to 2023). Trauma to the kidney. "CCl4 injection possibly leads to nephrotoxicity and acute/chronic kidney injury results in increased production of renal FGF23." (PMID 37396546, 2023). "Circulatory FGF23 levels are abnormally increased in pathological conditions like acute or chronic kidney injury, resulting in disease progression as well as increased rates of morbidity and mortality." (PMID 37396546, 2023). "However, a very rapid skeletal response to the induction of acute kidney injury has recently been demonstrated, where an acute kidney injury within one hour resulted in a significant increase in the skeletal derived phosphaturic hormone, FGF23." (PMID 25885328, 2015). "Nevertheless, treatment with vitamin D does appear to further reduce FGF23 cleavage even in the context of CKD, consistent with human data showing increased iFGF23 levels after calcitriol treatment in patients with kidney injury." (PMID 37681408, 2023). "In murine kidney injury models, FGF-23 influences leukocyte recruitment and host defense, which are restored after FGF-23 neutralization." (PMID 36012420, 2022).
psoriasis (6 papers, 2017 to 2025). An autoimmune condition characterized by red, well-delineated plaques with silvery scales that are usually on the extensor surfaces and scalp. "Nowadays, the use of fibroblast growth factors, namely 21 and 23 (FGF21, FGF23), are considered as a promising approach to assess the risk and diagnose the presence of psoriasis-related cardiometabolic abnormalities." (PMID 31847236, 2019). "Consequently, long-term psoriasis may predispose patients to Fibroblast growth factor-23-secreting tumors." (PMID 28852641, 2017). "The serum FGF23 concentration of participants with primary EP was significantly higher than that of participants with EP that had developed from other types of psoriasis (736.1 pg/ml vs. 441.0 pg/ml, p = 0.039)." (PMID 37593148, 2023). "Despite the existence of a broad spectrum of evidence, the exact role of FGF21 and FGF23 in psoriasis still requires further studies." (PMID 31847236, 2019). "There is growing evidence to suggest that Fibroblast growth factor-23 has a role in regulating immune function while an increased level of it may play a role in the pathogenesis of psoriasis." (PMID 28852641, 2017). "However, few studies have investigated serum FGF23 concentrations in patients with psoriasis." (PMID 37593148, 2023). "Relevant combinations of skin diseases and osteokines include FGF23 and psoriasis, cutaneous-skeletal hypophosphatemia syndrome, OCN and psoriasis, and LCN-2 and psoriasis." (PMID 38500951, 2024). "In addition, the serum FGF23 concentration significantly decreased during the treatment of patients with EP, suggesting that the serum FGF23 concentration may be related to the severity of psoriasis." (PMID 37593148, 2023). "In the case of FGF23, no significant changes were found between its concentration in patients with psoriasis and controls." (PMID 31847236, 2019). "Serum FGF23 concentrations did not correlate with total PASI score as well as did not respond with psoriasis severity in all three subgroups." (PMID 31847236, 2019). "In patients with moderate psoriasis, a significant (p < 0.05) negative correlation was demonstrated between the level of pre-treatment FGF21 and FGF23, and RBCs and HGB." (PMID 31847236, 2019).